TLR7 (toll like receptor 7)
Diseases named in the same sentence as TLR7 in open-access papers (continued):
Sharing a sentence is not in itself a finding about the gene and the disease.
psoriasis (continued). "The psoriasis‐like phenotype, including the skin’s epidermal thickness and infiltration by inflammatory cells, clinical score, and body weight, significantly improved in the Tlr7‐Y1025D mutant female mice (Tlr7ki/wt mice and Tlr7ki/ki mice) compared with the wild‐type mice." (PMID 34936223, 2022). "Hence, AZT may have the potential for psoriasis therapeutics through modulating TLR7 expression and function in skin DCs." (PMID 33510592, 2021). "In an rIL-23-induced psoriasis mouse model, a TLR-7,−8, and−9 antagonist inhibited the dermal expression of Nlrp3 and Aim2 and reduced the secretion of Th1 and Th17 cytokines in skin and serum, suggesting that inflammasomes might be a therapeutic target for psoriasis treatment." (PMID 32528469, 2020). "Thus, the effects of imiquimod on skin, which include antiviral activity and exacerbation of psoriasis, may be mediated through TLR7 in synergy with calcium." (PMID 24146965, 2013). "In addition, plasmacytoid DCs (pDC) also seems to play an important role in psoriasis, pointing to a potential pDC-based screening platform which could be generated using both TLR7 agonists and inflammatory cytokines." (PMID 20663192, 2010). "Recently, TLR-7 and TLR-9 have contributed to the development of autoimmune diseases such as rheumatoid arthritis, SLE, and psoriasis." (PMID 40651955, 2025). "It is a common model of induction of psoriasis as it activates the production of downstream factors like IL-6, IL-23, IL-1β, and TNF-α by binding to TLR-7 and stimulating epidermal plasma-like dendritic cells and macrophages." (PMID 40343294, 2025). "IMQ, which acts as a TLR7 agonist, activates the TLR7 signaling pathway, a crucial factor in IMQ-induced psoriasis-like skin inflammation and, equally important, in regulating keratinocyte proliferation and differentiation." (PMID 40873769, 2025). "To explore the dynamics of CD169+ macrophages during the progression of psoriasis, we utilized a well-established murine model in which IMQ, a toll-like receptor 7/8 agonist, was topically applied for six consecutive days." (PMID 38891893, 2024). "Topical application of IMQ, a ligand of Toll-like receptor 7 (TLR7) and TLR8, to the skin induces psoriasis-like manifestations in mice, where γδT cells are associated with disease development." (PMID 38348035, 2024). "In another mouse model where psoriasis was induced via TLR7, CLOCK and Per2 were found to regulate the severity of psoriasis via the direct modulation of the expression of IL23R." (PMID 36982706, 2023). "The synergistic action of TLR7 and imiquimod (IMQ, a TLR7 ligand) induces both the cytokines required to activate the Th17 pathway and the proinflammatory factor expression for psoriasis pathogenesis, and promotes IL-1, IL-2, and TNF-α production by DCs." (PMID 37160878, 2023). "Effects of IMQ are mostly mediated by the activation of TLR7 and TLR8 expressed on the immune cells, whereas mannan was shown to activate mannose receptor (CD206) on macrophages in psoriasis, psoriatic arthritis, and rheumatoid arthritis-like disease models." (PMID 36645209, 2023). "IMQ is a selective synthetic agonist to toll-like receptor 7/8 (TLR7/8), though it is advantageous, this specificity precludes mimicking many natural ligands that are involved in the induction of psoriasis." (PMID 36645209, 2023). "As expected, the application of the TLR7 agonist IMQ resulted in erythematosus, thickened and scaly psoriasis-like dermatitis, as confirmed by histological observation of hyperkeratosis, dyskeratosis, acanthosis, and dermal inflammatory cell infiltration." (PMID 35801590, 2022). "The results showed that the Psoriasis Area Severity Index score was decreased in psoriasis patients treated with immune modulatory oligonucleotide- (IMO-) 3100, an antagonist of TLR7 and TLR9." (PMID 35619184, 2022).
psoriasis (continued). "The focus of this work was to evaluate the role of Dsg-4 in modulating skin inflammation following administration of topical imiquimod (IMQ), a Toll Like Receptor 7 (TLR7) ligand, which is experimentally used to emulate a psoriasis-like dermatitis." (PMID 33995349, 2021). "PDCs infiltrate inflammatory psoriatic skin and produce large amounts of IFN-α on viral stimulation via TLR-7 and TLR-9, subsequently triggering T-cell cascade to potentiate Th1 cell bias and initiate psoriasis." (PMID 34733291, 2021). "IMQ, which serves as a ligand for TLR7 and TLR8 and as an effective immune activator, can be topically used to induce psoriasis-like skin lesions in a mouse model." (PMID 35153762, 2021). "It is well known that IMQ is a ligand of Toll-like receptor 7 (and TLR8 in humans) and recapitulates some of the immunological events in psoriasis patients." (PMID 33990689, 2021). "Real-time polymerase chain reaction (PCR) revealed that the expression levels of TLR3, TLR5, TLR6, TLR7, TLR9, and TLR10 in lesional skin were higher than those in peripheral blood mononuclear cells (PBMCs) of the same patients with psoriasis." (PMID 34790055, 2021). "The exposure of the mouse skin to the Toll-like receptor 7 (TLR7) and TLR8 agonist IMQ can mediate phenotypic changes closely resembling those in psoriasis via the IL-23/IL-17 immune response." (PMID 34745116, 2021). "Our in vivo studies showed that TAC5-a promisingly reduces the severity of psoriasis lesions in C57BL/6 mice induced by the application of IMQ, a TLR7 agonist." (PMID 32660060, 2020). "Topical application of IMQ, an effective agonist of TLR7 in mice (TLR7 and TLR8 in humans), can induce and exacerbate psoriasis by activating the IL-23/Th17 pathway via TLR724,25." (PMID 32873845, 2020). "In the present study, MHP1-AcN was shown to inhibit TLR7/8 agonist-induced IL-6 production in RAW 264.7 cells and in a mouse model of psoriasis at the early stage of disease." (PMID 31659208, 2019). "Similar to psoriasis, LL37 can also complex with self-RNA, stabilize, and internalize it for TLR7 activation and promote inflammation and ANA production." (PMID 31105556, 2019). "In an imiquimod (IMQ), a toll-like receptor 7 (TLR7) agonist, induced mouse model of psoriasis, S1P exhibited anti-proliferative effects on dermal cells and anti-inflammatory effects by preventing immune cell, particularly DC, infiltration." (PMID 31357710, 2019). "Given DCs have been shown to play an essential role in psoriasis development, we stimulated WT and MKP-1−/− BMDCs with TLR7/8 ligands R848 and measured the cytokine expression." (PMID 29619028, 2018). "Aldara cream, containing TLR7 agonist IMQ, has been used to induce psoriasis-like inflammation characterized by increase in epidermal thickness, erythema and scaling." (PMID 30279326, 2018). "We studied the potential beneficial effect of isoflavone extract in a murine IMQ-induced psoriasis-like skin inflammation model in which IMQ, a TLR7/8 agonist, was applied to the whole back of the mice daily over 6 days." (PMID 29679037, 2018). "IMO-3100, a TLR7/9 antagonist, and IMO-8400, a TLR7/8/9 antagonist, suppressed inflammation in a mouse model of psoriasis." (PMID 25538618, 2014). "A TLR7/8 agonist used to treat skin abnormalities such as cancerous lesions, IMQ, has been shown to exacerbate psoriasis in patients." (PMID 24386404, 2013). "Recently, activation of human dendritic cells through TLR7 and TLR8 by self RNA-antimicrobial peptide complexes provided new insights into the mechanism that provokes the auto-inflammatory responses in psoriasis." (PMID 24146965, 2013). "Additionally, although results of the clinical trial of the TLR7/9 antagonist are still being analyzed, transcriptomic data from the IL-23 model herein provides biomarker pathways that may be analyzed in psoriasis patients undergoing trials with TLR antagonists." (PMID 24386404, 2013).
psoriasis (continued). "Recently, the TLR7 and 9 antagonist used in this study, IMO-3100, was tested in a Phase 2 psoriasis treatment trial." (PMID 24386404, 2013). "In particular, IFN-α produced by pDCs upon recognition of foreign nucleic acids via TLR7 and TLR9 contributes to tolerance breakdown in several autoimmune diseases, such as SLE, SS, and psoriasis." (PMID 22826711, 2012). "With this in mind, despite the limitations, our study emphasises the potential role for TLR7 signalling in human psoriasis, and highlights the usefulness of the IMQ-induced psoriasis mouse model as a tool to study the TLR7/c-Rel signalling axis in disease development." (PMID 39586195, 2024). "In addition, topical IMQ in patients can exacerbate previously controlled psoriasis in both IMQ-treated and uninvolved distant skin sites further emphasising the role of TLR7 signalling in psoriasis pathogenesis." (PMID 39586195, 2024). "Taken together, these results suggest that TLR7 signalling does not affect keratinocyte proliferation and c-Rel is dispensable for the expression of psoriasis relevant inflammatory cytokines in HaCaT cells." (PMID 39586195, 2024). "Besides, as one of the genes in the TLR7 regulatory pathway, GRAMD1A can be used to assess the response of psoriasis after treatment." (PMID 35860689, 2022). "Recent studies have found that certain factors regulate the AIM2 inflammasome signaling pathway and participate in the pathogenesis of psoriasis, including prokineticin 2 (PK2), caspase recruitment domain family member 18 (CARD18), aurora kinase A (AURKA), TLR-7, TLR-8, and TLR-9 antagonists." (PMID 36118867, 2022). "By dephosphorylating TLR7 at Tyr1024 and inducing TLR7 ubiquitination, SHP2 drove the trafficking of TLR7 to the endosomes, which sustained the activation of downstream TLR7/NF‐κB signaling, thereby promoting the development of psoriasis." (PMID 34936223, 2022). "Interestingly, Datura metel L.—a traditional Chinese medicine known to suppress the progression of IMQ‐induced psoriasis in a the mouse model—can suppress TLR7 and TLR8 expression and inhibit the activity of the TLR7/8‐MyD88‐NF‐κB‐NLRP3 inflammasome pathway." (PMID 34936223, 2022). "Therefore, c-Jun/AP-1 is a central driver of TLR7-induced immune responses by DCs and JNK/c-Jun a potential therapeutic target in psoriasis." (PMID 33724710, 2021). "In conclusion, elevated expression levels of TLR1, TLR2, TLR4, TLR7, and TLR9 may facilitate the occurrence of psoriasis." (PMID 34790055, 2021). "In this imiquimod-induced psoriasis model, TLR7 and TLR9, but not TLR7 or TLR9 alone, are required for its pathogenesis, suggesting DNA recognition is important for the development of disease." (PMID 33633744, 2020). "For diseases where LL-37 may activate TLR7 and TLR9 signaling, such as psoriasis and SLE, an antagonist drug of LL-37 may provide a novel therapeutic strategy." (PMID 32927756, 2020). "Topical application of imiquimod, a ligand of TLR7 and TLR8, induces a psoriasis-like skin inflammation with typical microscopic and macroscopic psoriatic markers in mice, and is the most commonly used psoriasis animal model." (PMID 32106600, 2020). "IMQ is a ligand for Toll like receptors (TLR7 and TLR8) and when topically applied produces psoriasis-like skin lesions in mice which display many of the same characteristics as those observed in psoriasis in humans; elevations of IL-23/IL-17 and the dependency upon IL-22 to develop the lesions." (PMID 25965695, 2015). "Indeed, the use of the TLR7 and TLR8 agonist imiquimod in patients with cancer exacerbates psoriasis." (PMID 23593527, 2013). "This has given rise to the notion that under certain conditions, e.g., in psoriasis patients, tolerance to self-DNA and -RNA can be ‘accidentally’ broken by LL37 involving the nucleic acid-sensing Toll-like receptor (TLR) 7, TLR8 (ssRNA) and TLR9 (DNA) in humans, and Tlr7, Tlr13 and Tlr9 in mice." (PMID 38783164, 2024).
psoriasis (continued). "The role of c-Rel has also been shown in TLR2, 3, 4, 6, and 9-induced activation of the IL-23p19 promoter, however there is a lack of knowledge regarding the potential role of c-Rel in TLR7 signalling, and the possibility of this signalling axis being involved in the development of psoriasis." (PMID 39586195, 2024). "This study revealed that topical administration of astilbin at a lower dose targeted the TLR7/8 signalling pathway, subsequently inhibiting Th17/IL‐17A‐induced immune responses and excessive keratinocyte proliferation to ameliorate IMQ‐induced psoriasis‐like skin lesions in SKH‐1 mice." (PMID 35023281, 2022). "Consequently, SHP2‐mediated TLR7/NF‐κB activation was augmented, leading to further increases in the expressions of psoriasis‐related inflammatory cytokines, including IL‐23A, TNF‐α, IL‐6, and IL‐1β, thus accelerating psoriasis‐like skin inflammation." (PMID 34936223, 2022). "Thus, the protein expression levels of TLR7 and TLR8 in IMQ-induced psoriasis mice were detected." (PMID 31181689, 2019). "Our present study showed that the protein expression levels of TLR7, TLR8, MyD88, and p-NF-κB in the skin of mice induced by IMQ were upregulated significantly; consequently, TLR7/8–MyD88–NF-κB signaling was considered to play a critical role in IMQ-induced psoriasis." (PMID 31181689, 2019). "The responsiveness to TLR7 and TLR8 stimulation is relevant for the activation of slanMo in autoimmune diseases and psoriasis where single stranded RNA motives are either contained within autoimmune complexes or being complexed by the antimicrobial peptide LL37 as in psoriasis." (PMID 31191513, 2019). "Hence, we hypothesised that the cellular mechanism controlled by TLR7/c-Rel axis in psoriasis pathogenesis was likely not through its cell intrinsic function in keratinocytes." (PMID 39586195, 2024). "Thus, the lack of IL-10 expression under the TLR7 signaling and the constitutive upregulation of IL-23 in DCs could result in the exacerbation of imiquimod-induced psoriasis-like skin inflammation." (PMID 32456211, 2020). "Our study indicated that EPD could alleviate psoriasis in the IMQ-induced mice model and that the potential mechanisms that were involved were, at least in part, due to inhibiting the inflammation responses via the TLR7/8–MyD88–NF-κb–NLRP3 inflammasome signaling pathway." (PMID 31181689, 2019). "Moreover, stimulation of the antiviral pattern recognition receptors such as TLR7/8 with IMQ, a synthetic agonist, is sufficient to trigger psoriasis‐like skin inflammation in mice and psoriasis in humans, indicating that the antiviral signaling pathway may be involved in its etiologic mechanism." (PMID 28377495, 2017). "Fourthly, the signaling molecules involved in HFD- or propionate-induced attenuation of psoriasis-like dermatitis have not been clarified and should comprehensively be analyzed, such as NF-κB, STAT3, mTOR, or TLR7." (PMID 37762500, 2023). "Blockage of JNK/c-Jun signaling, which is required for the TLR7-IMQ mediated inflammation but not for normal DC skin development, was found to reduce the DC IL-23 production and relieve the psoriasis-like skin inflammation." (PMID 34361107, 2021).
autoimmune disease (148 papers, 2009 to 2026). A disorder resulting from loss of function or tissue destruction of an organ or multiple organs, arising from humoral or cellular immune responses of the individual to their own tissue constituents. "Hyper-responsiveness of TLR7 has been implicated in the development of murine models of autoimmune diseases such as SLE and psoriasis." (PMID 40910948, 2026). "TLR7 is an example of a dosage‐sensitive X‐linked gene where overexpression or increased protein activity is associated with autoimmune disease." (PMID 41574968, 2026). "Approximately 10% of the genes encoded by the X chromosome are involved in immune functions, including TLR7, and increased number of X chromosomes has been associated with higher risk of autoimmune disease." (PMID 40741215, 2025). "TLR7 has received significant attention in relation to understanding the mechanisms underlying the female predisposition to autoimmune diseases, as it plays a critical role in the immune response and is encoded on the X chromosome." (PMID 41012652, 2025). "TLR7 has also been implicated in the progression of Parkinson’s disease, Alzheimer’s disease, and autoimmune diseases such as systemic lupus erythematosus and atherosclerosis." (PMID 40329535, 2025). "Elevated TLR7 expression in women has long been proposed to contribute both to their enhanced responses to infection and their increased susceptibility to autoimmune diseases." (PMID 41516251, 2025). "Mutation of three amino acids in the UNC93B1 C-terminal tail in mice caused TLR7-dependent autoimmune disease, and a coding variant in the same region has been linked to exfoliative cutaneous lupus in dogs." (PMID 38780621, 2024). "TLR7 has also been linked to the pathogenesis of other autoimmune diseases besides SLE, including type 1 diabetes and Sjögren’s disease, by increasing type I IFNs." (PMID 39286970, 2024). "Since TLR7 is implicated in several autoimmune diseases and this receptor relies on MyD88 for signaling, we sought to examine the role of Tlr7 in pSD." (PMID 39310226, 2024). "The increased TLR7 activity in females is associated with a higher prevalence of autoimmune diseases, such as SLE, and reduced efficacy of TLR7-targeted therapies in males." (PMID 39731171, 2024). "In summary, pDCs are important players in the mechanisms underlying several autoimmune diseases and demonstrate enriched inflammatory responses through the activation of TLR7/8 and TLR9 signaling pathways and the IFN system." (PMID 36359340, 2022). "Here, we characterize the effects of prenatal activation of TLR7, which is implicated in the pathogenesis of autoimmune disease." (PMID 30610201, 2020). "We then evaluated autoimmune disease parameters, kidney disease, and response to in vivo TLR7/9 pathogenic signals." (PMID 32251357, 2020). "Polymorphisms in four genes encoding proteins that control the MyD88-IRAK4-IRAK1 pathway have been reported to predispose to SLE and other autoimmune diseases in many human populations, namely, TLR7, IRAK1, TNIP1, and TNFAIP3." (PMID 31694920, 2019). "TLR7, recognizing single-stranded RNA and guanosine analogs, is one of the well-known pathogenic factors of autoimmune disease model." (PMID 29988708, 2018). "Considering the importance of variations in TLR7 levels for the susceptibility to autoimmune disease in humans, a potential involvement of TLR7 in the differences in susceptibility to Resiquimod-induced heart disease between strains was investigated." (PMID 28250051, 2017). "The release of these endogenous TLR agonists has been suggested as a mechanism of perpetuating inflammation in autoimmune diseases and TLR7 has been particularly implicated, making this TLR a candidate for targeted therapy." (PMID 26076454, 2015). "In a murine model of spontaneous lupus, it was shown that TLR7 deficiency results in decreased serum levels of IgG2a and IgG3 isotypes, which are among the pathogenic isotypes in autoimmune diseases such as SLE." (PMID 22691272, 2012).